TSN (translin)
Description:
DNA-binding protein that specifically recognizes consensus sequences at the breakpoint junctions in chromosomal translocations, mostly involving immunoglobulin (Ig)/T-cell receptor gene segments. Seems to recognize single-stranded DNA ends generated by staggered breaks occurring at recombination hot spots. Exhibits both single-stranded and double-stranded endoribonuclease activity. May act as an activator of RNA-induced silencing complex (RISC) by facilitating endonucleolytic cleavage of the siRNA passenger strand.
Synonyms: C3PO; TRSLN; BCLF-1; REHF-1; RCHF1; TBRBP
Tractability: Small molecule: it has a binding pocket of medium quality. PROTAC: ubiquitination databases record sites on it; its protein half-life has been measured.
Target class: Enzyme; Hydrolase
Gene: Protein-coding gene on chromosome 2 (121,737,103 to 121,767,853, forward strand). Ensembl gene ENSG00000211460.
Subcellular location: Cytoplasm; Nucleus
Subcellular location (Human Protein Atlas): Endoplasmic reticulum; Nucleoplasm
Pathways (Reactome):
Gene expression (Transcription): Small interfering RNA (siRNA) biogenesis
Gene Ontology:
Molecular function: identical protein binding; protein binding; single-stranded RNA binding; DNA binding; mRNA binding; nucleic acid binding; RNA binding; sequence-specific DNA binding; single-stranded DNA binding
Biological process: RISC complex assembly; siRNA processing; regulatory ncRNA-mediated post-transcriptional gene silencing; RNA metabolic process
Cellular component: cytoplasm; endoribonuclease complex; nucleoplasm; nucleus; cytosol
Genetic constraint (gnomAD): Loss-of-function variants: 3 observed, 25.1 expected, observed/expected ratio (o/e) 0.12, 90% interval 0.053 to 0.31. The upper end of that interval is the gene's LOEUF score, 0.31, which puts it in group 1 of 6, group 1 being the genes least tolerant of losing a copy. Missense variants: 134 observed, 255.78 expected, observed/expected ratio (o/e) 0.52, 90% interval 0.45 to 0.61. Synonymous variants: 99 observed, 98.25 expected, observed/expected ratio (o/e) 1.01, 90% interval 0.86 to 1.19.
Homologues: Orthologues: chimpanzee TSN (100% identical), guinea pig TSN (100% identical), macaque TSN (100% identical), rabbit TSN (99% identical), mouse Tsn (99% identical), pig TSN (98% identical), rat Tsn (93% identical), dog TSN (91% identical), zebrafish tsn (79% identical), tropical clawed frog tsn (78% identical), Drosophila melanogaster trsn (52% identical). Paralogues in human: TSNAX (25% identical).
Diseases named in the same sentence as TSN in open-access papers:
TSN is named in the same sentence as 17 diseases in open-access papers, as found by Europe PMC text mining. Sharing a sentence is not in itself a finding about the gene and the disease. The quoted sentences say what the papers report.
depression (2 papers, 2010 to 2020). "Whereas FMRP seems to predominantly play a role in certain forms of synaptic depression, translin/trax complex appears to function in specific forms of both synaptic potentiation and depression." (PMID 33172471, 2020). "A recent study showed that the mutation G196A (Val66Met) in the BDNF coding sequence, which is linked to impaired episodic memory and depression in humans, disrupts a recognition site in BDNF mRNA for the RNA-binding protein translin." (PMID 20507609, 2010).
dysgerminoma (1 paper, 2009). A malignant germ cell tumor characterized by the presence of a monotonous primitive germ cell population. "Expression of genes TRC8 and TSN was tested both on dysgerminoma and in the proposita and her father." (PMID 19642973, 2009). "TSN was expressed approximately 3 times more in the testis than in normal ovary, while it was expressed approximately two times less in the dysgerminoma." (PMID 19642973, 2009). "Translin is underexpressed in the dysgerminoma compared to normal ovary." (PMID 19642973, 2009). "A role for TRC8 in dysgerminoma may relate to its interaction with Translin." (PMID 19642973, 2009). "In our patient Translin (TSN), a protein involved in post-transcriptional regulation of TRC8 and of a number of genes during spermatogenesis, is expressed two times less in the dysgerminoma than in normal ovary." (PMID 19642973, 2009).
fragile X syndrome (1 paper, 2020). A genetic syndrome caused by mutations in the FMR1 gene which is responsible for the expression of the fragile X mental retardation 1 protein. "Additionally, translin knockout (KO) mice, which lack translin/trax, exhibit some of the behavioral abnormalities found in a mouse model of fragile X syndrome (fragile X mental retardation protein-FMRP-KO mice)." (PMID 33172471, 2020).
hepatocellular carcinoma (1 paper, 2016). A malignant tumor that arises from hepatocytes. "It has been shown that the expression of human TSN (a.k.a., SND1) is upregulated in various human cancers such as colon, prostate, breast, and hepatocellular cancers." (PMID 26808625, 2016).
Hypertension (1 paper, 2022). The presence of chronic increased pressure in the systemic arterial system. "The function of Translin in other processes also indicates that regulating its activity might be of additional clinical utility, for example, deletion of Tsn (Translin gene) in mice reduces hypertension-related vascular stiffening by maintaining levels of a regulatory miRNA." (PMID 35714159, 2022).
lung adenocarcinoma (1 paper, 2015). A carcinoma that arises from the lung and is characterized by the presence of malignant glandular epithelial cells. "This suggests that TSN and S100A11 represent promising therapeutic targets to combat lung adenocarcinomas." (PMID 25940438, 2015). "Moreover, strong upregulation of TSN protein, ranging from about a two- up to a 12-fold increase in NSCLC species compared to the adjacent normal tissues was detected in each of 17 pairs of lung adenocarcinomas and the corresponding normal tissues analyzed in this study." (PMID 25940438, 2015).
lung carcinoma (1 paper, 2015). "Therefore, we aimed to investigate the role of TSN in the functioning of cell death machinery and its impact on the chemoresistance mechanisms of lung cancer." (PMID 25940438, 2015). "However, TSN's role in lung cancer apoptotic response to chemotherapy is unclear and in-depth investigations remain to be carried out." (PMID 25940438, 2015). "TSN (Tudor-SN), a multifunctional protein, is ubiquitously expressed and highly conserved from yeast to human suggesting its functional importance in varied cellular contexts; however, a comprehensive role of this protein in most of the tumors, including lung cancer, remains unknown." (PMID 25940438, 2015).
mental disorder (1 paper, 2018). A disease that has its basis in the disruption of mental process. "Given that aberrant profiles of miRNAs and their targeted genes have been implicated in mental disorders (such as schizophrenia, bipolar disorder and autism), the role of abnormal TRAX/translin regulation in mental disorders warrants future investigations." (PMID 30285728, 2018).
neuroblastoma (1 paper, 2013). Neuroblastoma (NB) is the most common solid, extracranial childhood tumor. "Consistent with previous reports, downregulation of mTdp-43 in mouse N2a neuroblastoma cells by small inference RNA (siRNA) significantly increased the levels of the abnormal splicing variants: mSort1+Ex17b (sortilin 1 including exon 17b) and mTsn_ΔEx5 (translin with exon 5 deletion) (siTardbp)." (PMID 23922830, 2013).
tumor (7 papers, 2015 to 2025). "For example, murine Translin is also implicated in survival of T cells required for immunological tumour suppression, so oncological therapeutic targeting needs to avoid diminution of such beneficial activities." (PMID 35714159, 2022). "The Translin-Trax complex also degrades the precursors to tumour suppressing microRNAs in cancers deficient for the RNase III Dicer." (PMID 35714159, 2022). "TSN is highly expressed in prostate cancer tissues, where it intensifies even more along with the tumor's aggressiveness." (PMID 25940438, 2015). "For example, TSN could be considered to be a potential analgesic, anti-inflammatory, anti-tumor, and antioxidant agent." (PMID 33011900, 2020). "This has led to the suggestion that Translin and Trax could provide drug targets in Dicer haploinsufficient tumours." (PMID 27183912, 2016). "The dose‐dependent anti‐tumor effect of TSP‐TN showed to induce massive amounts of apoptosis of the tumor cells in contrast to the control, Taxol, TSP, and TSN groups." (PMID 37632708, 2023). "Importantly, a direct role in oncogenesis has recently been reported for Translin and Trax in cancers that are haploinsufficient for Dicer, as they degrade pre-microRNAs that would be processed to microRNAs by a full Dicer complement to maintain tumour suppression." (PMID 27183912, 2016).
cancer (5 papers, 2015 to 2022). A tumor composed of atypical neoplastic, often pleomorphic cells that invade other tissues. "Translin and Trax (individually or in a Tn-Tx complex) are implicated in an array of biological processes, many of which influence human neurological function and disease, including cancer." (PMID 35714159, 2022). "Gene expression analysis performed using A549 NSCLC cells after silencing of TSN revealed several novel candidates for anti-cancer therapy downstream from TSN, such as S100A11, ATP6V1F, MDC1, BNIP3, etc., which are implemented in the cell death mechanism." (PMID 25940438, 2015). "However, both the function of TSN during normal development and the molecular mechanism of TSN in cancer cells still remain elusive." (PMID 26808625, 2016). "This association strongly emphasizes that unrestricted activation of TSN may result in hyperactivation of many such genes that eventually can lead to cancer initiation and progression." (PMID 25940438, 2015). "As cPLA2 was upregulated in 64% of NSCLC samples overexpressing S100A11, compared to normal tissues, targeting TSN or S100A11 may be particularly beneficial for anti-cancer treatment in these cases." (PMID 25940438, 2015). "Some of the genes, for example, TSN and MYB, are potential regulators of proliferation and so this could indicate that TEX19 is required by cancer cells to drive proliferation by maintaining sufficient levels of oncogenic transcripts." (PMID 28446200, 2017).
infection (5 papers, 2009 to 2026). The state of being infected such as from the introduction of a foreign agent such as serum, vaccine, antigenic substance or organism. "To determine whether Ago2, Dicer-2 or TSN expression levels are modulated during DENV2 infection, we used quantitative real-time PCR to measure component mRNA levels in midguts at the initial site of infection." (PMID 21356105, 2011).
genetic diseases (1 paper, 2022). "The conserved nucleic acid binding protein Translin contributes to numerous facets of mammalian biology and genetic diseases." (PMID 35714159, 2022). "This provides genetic insight into the longstanding question of how Translin might influence chromosomal rearrangements in human genetic diseases and provides important functional understanding of an oncological therapeutic target." (PMID 35714159, 2022).
TSN also shares sentences with these, for which no sentence is quoted: gastric atrophy (1 paper); hyperthyroidism (1); latent infection (1); lymphoma (1).